CFTR (CF transmembrane conductance regulator)
Diseases named in the same sentence as CFTR in open-access papers (continued):
Sharing a sentence is not in itself a finding about the gene and the disease.
cancer (continued). "Studies have introduced a range of diverse signals for each different tumor and its microenvironment that may underlie the contradictory activity of CFTR depending on the type of cancer, but the underlying mechanisms are yet under investigation." (PMID 32182826, 2020). "Nevertheless, the possibility cannot be ruled out that other mechanism(s) may also be working in other cell types or that different CFTR gene mutations could be found when comparing different cancer cells." (PMID 24212662, 2011). "In addition to CFTR variants, our cancer cohort had a high frequency of other known somatic cancer risk variants which could have been the major driver of cancer, or alternatively, CFTR may have added an increased risk variant." (PMID 41147257, 2025). "Besides its primary role as an anion channel, CFTR has been implicated in various cellular processes, including epithelial differentiation/polarization, tissue regeneration, foetal development, proliferation and cancer." (PMID 40910003, 2025). "While historically having a heterozygous CFTR pathogenic variant (PV) was once thought to be relatively benign, data are emerging that dysfunction of CFTR in either people with CF or carriers of a single CFTR PV may increase risk of cancer and other diseases." (PMID 41147257, 2025). "Both ABCC6 and ABCC7/CFTR have also been shown by others to harbor mutations that impair function and lead to disease, suggesting they may serve as cancer‐specific vulnerabilities." (PMID 40641097, 2025). "However, organ-specific cancer risks may be linked to the different localization and expression of the CFTR gene, as well as the different sensitivities of individual organs." (PMID 40563468, 2025). "The secondary aim of this study was to explore biological mechanisms for how CFTR PVs may increase cancer risk by investigating associations between germline CFTR PVs with (a) known germline cancer predisposition variants and (b) known somatic oncogenic driver mutations." (PMID 41147257, 2025). "Furthermore, CFTR has been implicated in drug resistance in certain cancers." (PMID 37686519, 2023). "In the future, the use of CFTR modulators may influence cancer risk among CF patients." (PMID 36483264, 2022). "Thus, CFTR is posited to influence the renewal process of the intestinal epithelium and loss of CFTR expression may directly influence cancer initiating cells progression." (PMID 33363037, 2020). "However, given that deficiency for CFTR has been reported in a wide range of cancers that arise independently of Wnt/β-catenin signaling, it is likely that CFTR’s function as a tumor suppressor in CRC extends beyond influencing the intestinal stem cell compartment and Wnt/β-catenin signaling." (PMID 32326161, 2020). "In addition, we cannot rule out the possibility that mechanisms channeling GSH efflux differ when comparing different cancer types, or that, e.g., different CFTR gene mutations, could be found when comparing different cancer cells." (PMID 24212662, 2011). "CFTR serves as the major source of chloride secretion in the murine intestine, and its disruption can lead to inflammation, dysbiosis, and cancer." (PMID 40051209, 2025). "CFTR dysfunction is also highly relevant given the growing evidence that CFTR functions as a tumour suppressor gene which can alter cancer cell proliferation and metastasis." (PMID 40368426, 2025). "The observed enrichment of CFTR PVs varied by cancer type, with CFTR PVs being overrepresented in patients with skin and gastrointestinal cancers." (PMID 41147257, 2025). "One possible explanation for the higher incidence of cancer in the digestive tract compared to the respiratory tract is due to the reduction in expression of CFTR after birth, which remains minimal in adult respiratory epithelia." (PMID 40563468, 2025).
cancer (continued). "PTEN is known to play an important role in maintenance of epithelial polarity, EMT, and cancer progression, and the transcription signatures of these pathways were altered in CFTR-KO PDEs." (PMID 39687022, 2024). "One of the key aspects of CFTR’s role in cancer is its influence on ion transport and cellular homeostasis." (PMID 37686519, 2023). "One woman with CF compared the impact of starting a CFTR modulator on her perception of the future to a cancer diagnosis in a “seemingly healthy person”." (PMID 37189913, 2023). "CFTR-mediated drug resistance can impact the effectiveness of cancer treatment and pose challenges in achieving successful outcomes." (PMID 37686519, 2023). "Dysregulation of CFTR can have profound effects on cancer development and progression, further elucidating the molecular mechanisms underlying CF." (PMID 37686519, 2023). "The potential impact of CFTR dysfunction on these cancers requires more comprehensive studies to establish a clearer association." (PMID 37686519, 2023). "The role of the CFTR gene in the development and progression of cancers in patients with CF is an emerging area of research." (PMID 37686519, 2023). "Even though CFTR has been proposed as a tumor suppressor gene, its upregulation has been described in some types of cancers." (PMID 37104011, 2023). "Initially recognized for its involvement in CF, CFTR has emerged as a potential player in cancer development and progression." (PMID 37686519, 2023). "The role of CFTR in cancer is an intriguing area of investigation that has gained substantial interest in recent years." (PMID 37686519, 2023). "The activity of CFTR can affect the response of cancer cells to chemotherapeutic agents by influencing drug uptake, efflux, and intracellular concentration." (PMID 37686519, 2023). "For the first time in Russia, a full-scale molecular genetic study of the CFTR gene was carried out in patients with malignant neoplasms." (PMID 37175647, 2023). "By understanding how CFTR and cancer are connected, doctors can develop better ways to screen for and treat these cancers in people with CF." (PMID 37686519, 2023). "Thus anabolic effect of CFTR modulators might influence cancer risk." (PMID 36941680, 2023). "In summary, CFTR plays a multifaceted role in cancer, influencing various aspects of tumor biology, including ion transport, EMT, inflammation, cellular proliferation, and drug response." (PMID 37686519, 2023). "The development of a very EO-CRC can be explained by the adverse circumstance of the co-occurrence of CFTR mutations and IC2 LoM, likely responsible for cancer initiation and further triggered by somatic events enhancing the WNT/beta-catenin pathway." (PMID 37046605, 2023). "Further research is needed to clarify the relationship between CFTR modulator therapy and cancer development in CF patients." (PMID 37686519, 2023). "CFTR has been found to act as a tumor suppressor in various cancer types and its expression is generally downregulated in tumors." (PMID 35743652, 2022). "The effects of CFTR silencing in promoting cancer invasiveness was found to be reversed in the presence of NF-κB inhibitors, thereby highlighting the regulation of this pathway by CFTR." (PMID 35743652, 2022). "The expression levels of CFTR mRNA and protein were found to be silenced by epigenetic mechanisms, mainly hypermethylation of the CFTR promoter, in several of the major cancers where CFTR has been shown to act as a tumor suppressor." (PMID 35743652, 2022). "It needs to be mentioned herein that PLB was able to suppress the activities of intestinal Ca2+-activated Cl− channels and the cystic fibrosis transmembrane conductance regulator (CFTR) or other types of Cl− channels in cancer cells." (PMID 35453530, 2022). "PAI-1 also controls the urokinase plasminogen activator (uPA) cancer pathway that is blocked by functional CFTR." (PMID 35500936, 2022).
cancer (continued). "Several studies suggest that CFTR exerts variable effects in different tissues and in different cancer types." (PMID 35042562, 2022). "Emerging evidence suggests that CFTR plays critical roles in modulating a wide variety of cellular processes involved in cancer development, such as cell growth, survival, migration and invasion." (PMID 32463592, 2020). "In parallel, many studies report an actual functional role for CFTR in cancer suppression, while dysfunctional CFTR promotes cancer development both in vitro and in vivo." (PMID 32365523, 2020). "This mechanistic link is a plausible explanation for the high incidence of fibrosis and cancer in CF, as well as for the role of CFTR as tumour suppressor protein." (PMID 33106471, 2020). "Although we did detect a CFTR band in one of these cancer samples, the band was weaker than that in normal tissue, suggesting downregulation of CFTR." (PMID 32182826, 2020). "Further experiments demonstrated that CFTR CpG islands were hypermethylated in cancer cells and tissues and hypomethylated in normal cells and tissue." (PMID 32182826, 2020). "In parallel, multiple studies also report an actual functional role for CFTR as a tumour suppressor gene, whereas dysfunctional CFTR promotes cancer development both in vitro and in vivo." (PMID 32365523, 2020). "While epigenetic modulation has been studied in a few cancers, epigenetic regulation of cystic fibrosis transmembrane conductance regulator (CFTR) in HNC has yet to be reported." (PMID 32182826, 2020). "This is followed by CFTR (18 cancer types) and four other genes that were amplified in 17 cancer types (ADIPOR2, LEP, PRKAG2 and RHEB)." (PMID 32807122, 2020). "Many other early studies supported this hypothesis, claiming an inverse association between CFTR gene mutations and the incidence of several cancers, thus suggesting that mutant CFTR (in its heterozygous form) might have a protective role against certain cancers." (PMID 32365523, 2020). "From 1990 onwards, an increasing number of studies reported a possible role for CFTR both as an oncogene and as a tumour suppressor gene in several types of cancer." (PMID 32365523, 2020). "Some light on the role of CFTR in cancer seems to be shed by its connection to the process of epithelial–mesenchymal transition (EMT) which is discussed in the next section." (PMID 32365523, 2020). "We closely examined CFTR activity in cancer characteristics and potential signaling compared to other tumors." (PMID 32182826, 2020). "We then studied CFTR expression in four pairs of human cancer tissue samples and found that CFTR was silenced in three out of the four." (PMID 32182826, 2020). "In parallel with cancer, an increasing number of emerging studies show that CFTR plays a role in fundamental cellular processes such as foetal development, epithelial differentiation/polarization, regeneration, and epithelial–mesenchymal transition (EMT)." (PMID 32365523, 2020). "Given that MAPK pathway cross‐talks with Akt pathway in the regulation of cancer development, it is plausible that CFTR modulates Akt/Bcl2 via activation of MAPK." (PMID 32463592, 2020). "CFTR induction by 5-Aza-CdR treatment attenuated cancer characteristics while CFTR silencing promoted it via tumor invasion, anti-apoptosis, rapid growth, and high cell motility, indicating CFTR is significant in 5-Aza-CdR-induced anti-tumor activity in HNC." (PMID 32182826, 2020). "Thus, in addition to the correction of CFTR dysfunction, the new challenge in treating older patients might be to control the accelerated aging processes, which are associated with inflammation, tissue damage and cancer development." (PMID 30764828, 2019). "By inhibiting mesh collagen IV formation, T12 eliminates the protective barrier of epithelial progenitor cancer cells and impedes aberrant CFTR recruitment for xenobiotic extrusion." (PMID 29541394, 2018).
cancer (continued). "Meanwhile, the effect of CFTR gene on the expression of cancer stem cell related transcriptional factors was also detected by immunoblotting (Western blot) assay." (PMID 29526175, 2018). "Research examining the involvement of EMT in CF has been limited, focusing only on CFTR involvement in cancer and other fibrotic diseases." (PMID 30021582, 2018). "Selected aminoglycosides are being tested for their ability to read-through premature stop-codons in genetic mutations for the cystic fibrosis transmembrane conductance regulator (CFTR) and selected cancers." (PMID 29062271, 2017). "Given that miRNA levels and function in cancer cell lines often differs from primary cells, we examined miR-200b’s impact on CFTR expression in primary human lung cells (NHBEC Normal Human Bronchial Epithelial Cells) obtained from 3 donors." (PMID 29167681, 2017). "Apart from its channel function, CFTR has also been shown to be involved in multiple cellular processes including cancer development and metastasis." (PMID 28978008, 2017). "Previous studies from both our groups and others have also shown the correlation of CFTR expression levels and cancer prognosis in different cancers." (PMID 27769067, 2016). "It has been shown that CFTR can regulate Grp78 and NF-κB during embryo development and during cancer initiation." (PMID 27483469, 2016). "Apart from cancer, miR-1246 has been shown to be involved in the regulation of chloride transport in epithelial cells by targeting CFTR and SLC12A2 and in the regulatory phenotype of T cells." (PMID 25880556, 2015). "Notably, recent evidence suggests a potential association between CFTR modulation and alterations in immune response and systemic inflammation, which may influence the development of comorbidities that are traditionally less emphasized in CF, such as cancer and metabolic diseases." (PMID 41154689, 2025). "For this reason, our cohort is enriched for patients with progressive and treatment resistant cancers which could suggest that CFTR dysfunction may increase treatment resistance and is enriched in late‐stage patients." (PMID 41147257, 2025). "The KLF family of transcription factors, including both KLF4 and KLF6, have a well‐established role in cancer progression, and we showed direct regulation of CFTR by KLF5 in airway epithelial cells where this factor has a critical role in wound repair and innate immunity." (PMID 40785146, 2025). "Furthermore, CFTR dysfunction in the intestinal epithelium has been linked to a higher susceptibility for CRC, the third most common cancer with high mortality." (PMID 40066329, 2025). "Thus, the primary aim of this study was to determine the frequency of CFTR PVs in a cohort of adult patients with advanced cancer." (PMID 41147257, 2025). "In conclusion, the CFTR gene, responsible for the pathogenesis of CF, may also play a role in the development and progression of certain cancers in CF patients." (PMID 37686519, 2023). "In the current study, the reads spanning the 11.2-kbp inversion in CFTR showed that the enhanced read length enables a full capture of SVs, significantly improving cancer SVs detection efficacy, providing a powerful tool for cancer precision therapeutics." (PMID 36812239, 2023). "An association between cancer incidence and genetic variations in the CFTR gene has been suggested, even though the exact role of CFTR in cancer has not been elucidated." (PMID 36674481, 2023). "CFTR regulates cell proliferation and invasion, suggesting CFTR might be related to the oncogenesis of malignant tumors." (PMID 36941680, 2023). "Furthermore, CFTR has been implicated in the regulation of epithelial-mesenchymal transition (EMT), a fundamental process involved in cancer metastasis." (PMID 37686519, 2023). "Abnormal expression of CFTR has been observed in several types of cancer, however it is unknown if it affects the function of tumor-supressor or tumor-promoting genes." (PMID 36941680, 2023).
cancer (continued). "The dysregulated immune response in the presence of CFTR dysfunction may further contribute to cancer progression." (PMID 37686519, 2023). "The remaining one, a 45 years-old patient with the c.1521_1523delCCT pathogenic mutation in CFTR gene, had a negative family cancer history." (PMID 36717774, 2023). "Knockdown of the CFTR gene enhances the expression of urokinase-type plasminogen activator, a serine protease that plays a central role in extracellular matrix degradation, invasion, regulation of epithelial-mesenchymal transition and metastasis during cancer." (PMID 36941680, 2023). "Although the CFTR gene could act as a tumor suppressor, its roles in various cell types and cancer cells need to be defined." (PMID 35205604, 2022). "Thus, CFTR is well placed to influence intestinal crypt renewal and the activity of putative cancer progenitor cells." (PMID 35743652, 2022). "The pathogenesis of cancer in CF remains unclear, but inflammation and the role of CFTR have been discussed." (PMID 36483264, 2022). "Moreover, several cancer studies have identified CFTR as a tumor suppressor, whereby down-regulated CFTR favors cancer development both in vitro and in vivo." (PMID 35500936, 2022). "The results of studies on the roles of CFTR in cancer have been contradictory." (PMID 35205604, 2022). "Malfunctioning and/or abnormal expression of CFTR have been found in various types of cancer." (PMID 35205604, 2022). "Overall, these CFTR modulator drugs can represent a new class of personalized cancer medicine." (PMID 35743652, 2022). "CFTR promoter hypermethylation and gene silencing were also found in cancers outside the GI tract." (PMID 35743652, 2022). "CFTR is a cAMP-activated Cl–/HCO3– channel best known for causing the life-limiting cystic fibrosis disease through the F508del mutation, but mutations and differential expression are also linked to cancer predisposition." (PMID 34055797, 2021). "Gene expression is increased or reduced depending on the cancer type (CFTR,1)." (PMID 34055797, 2021). "Despite these findings, the role of CFTR in non‐epithelial cell‐derived cancers is completely unknown." (PMID 32463592, 2020). "Interestingly, CFTR mutations significantly reduced overall cancer survival rates (log-rank test, P-value = 1.13E-3), consistent with a possible tumor suppressor function of CFTR in human cancer." (PMID 34541464, 2020). "Thus, further studies are needed in order to better understand the elusive moonlight role(s) of CFTR in cancer." (PMID 32365523, 2020). "We then investigated the impact of CFTR on expressions and functions of cancer-related genes." (PMID 32182826, 2020). "However, up‐regulation of CFTR has also been reported, at which CFTR promotes cancer development in female reproduction system." (PMID 32463592, 2020). "The correlation between CFTR dysfunction and incidence of cancer has been reported for long time." (PMID 32463592, 2020). "Considering that F508del-CFTR cells are already more mesenchymal/cancer-like, we can then speculate that this transformation may have a higher relative impact on wt-CFTR cells." (PMID 32937756, 2020). "Accordingly, CFTR has been proposed to function as a tumour suppressor in a wide range of cancers." (PMID 33106471, 2020). "One area that cancer investigators might focus on is the influence of CFTR on the intestinal stem cell (ISC) compartment as ISCs are the source of putative CRC progenitor cells." (PMID 32326161, 2020). "We first assessed whether CFTR modifications affected the expression of other cancer-related genes in HNC." (PMID 32182826, 2020). "Data showed differential expression patterns for CFTR between normal and cancer cells and tissues." (PMID 32182826, 2020). "These previous studies on CFTR in other cancers, lead to a hypothesis that CFTR might be deeply related to metastasis, poor prognosis, or even poor survival rates." (PMID 32182826, 2020).